ALCAM (activated leukocyte cell adhesion molecule)
Diseases named in the same sentence as ALCAM in open-access papers (continued):
Sharing a sentence is not in itself a finding about the gene and the disease.
osteosarcoma (17 papers, 2012 to 2025). A usually aggressive malignant bone-forming mesenchymal neoplasm, predominantly affecting adolescents and young adults. "Federman identified an antigen associated with osteosarcoma cell surface (ALCAM) and alpha-AL-HPLN, a tailored anti-ALCAM-hybrid polymerized liposomal nanoparticle immune conjugate." (PMID 37007050, 2023). "We describe a novel osteosarcoma-associated cell surface antigen, ALCAM." (PMID 23024593, 2012). "The authors created an anti-ALCAM-hybrid polymerized liposomal nanoparticle immunoconjugate (α-AL-HPLN) to specifically target osteosarcoma cells and deliver a cytotoxic agent such as doxorubicin." (PMID 24082816, 2013). "Fluorescent nanoparticles coated with anti-ALCAM diabodies preferentially bind to osteosarcoma cell lines, even those that express ALCAM at relatively low levels." (PMID 23024593, 2012). "The quality of ALCAM expression was further confirmed in fluorescent immunohistochemistry showing primarily a membranous, surface component to the ALCAM expression in osteosarcoma cell lines." (PMID 23024593, 2012). "Our data clearly demonstrate an increase in ALCAM expression in osteosarcoma though the biologic consequences of this are difficult to gauge." (PMID 23024593, 2012). "We, then, create an engineered anti-ALCAM-hybrid polymerized liposomal nanoparticle immunoconjugate (α-AL-HPLN) to specifically target osteosarcoma cells and deliver a cytotoxic chemotherapeutic agent, doxorubicin." (PMID 23024593, 2012). "Binding studies were performed comparing the relative affinities of anti-ALCAM coupled PLNs (α-AL-PLN) versus untargeted PLNs towards osteosarcoma cell lines." (PMID 23024593, 2012). "All 6 osteosarcoma cell lines expressed ALCAM, and 5 of 6 demonstrated elevated expression at the level seen in the HPAF control." (PMID 23024593, 2012). "With these criteria in mind, the cell surface receptor activated leukocyte adhesion molecule (ALCAM, CD166) is an attractive candidate to target osteosarcoma." (PMID 23024593, 2012). "A molecular survey of the osteosarcoma cell line U2-OS demonstrated expression of ALCAM on the surface of these cells." (PMID 23024593, 2012). "We have shown that coupling anti-ALCAM diabodies to the surface of PLNs increases their binding affinity for osteosarcoma cell lines." (PMID 23024593, 2012). "In this paper, we demonstrate that ALCAM is overexpressed in both osteosarcoma tumor-derived cell lines and primary biopsy specimens." (PMID 23024593, 2012). "Additionally, FSTL1 knockdown in osteosarcoma inhibits proliferation, invasion, spheroid formation, and ALCAM expression, while anti-FSTL1 treatment restores NK cell activity, killing tumor cells and inhibiting osteosarcoma growth and metastasis." (PMID 38605354, 2024). "In this context, it is tempting to think that modulating ALCAM expression could potentiate the invasive and metastatic behaviors found in high-grade malignancies such as osteosarcoma." (PMID 23024593, 2012). "Though ALCAM may be a limited prognostic biomarker in osteosarcoma, it has potential to serve as a molecule through which to therapeutically target this tumor." (PMID 23024593, 2012). "Finally, we find that coating these hybrid liposomes with recombinant anti-ALCAM antibody further improves cytotoxic killing of osteosarcoma cell lines." (PMID 23024593, 2012). "Polymerized liposomes and hybrid polymerized liposomal nanoparticles (PLNs and HPLNs) were evaluated as a potential therapeutic delivery vehicle that could be targeted to osteosarcoma cells expressing ALCAM." (PMID 23024593, 2012). "In addition, differences in growth conditions between in vivo in osteosarcoma patients and in vitro in tissue culture may be responsible for changes in ALCAM expression." (PMID 23024593, 2012). "Currently, potential effective targets for CAR-T cell therapy in osteosarcoma include HER2, IGF1R, ROR1, EphA2, CSPG4, folate receptor with EC17, B7-H3, GD2, NKG2D, ALCAM/CD166, IL-11Rα, and FAP." (PMID 38187386, 2023).
osteosarcoma (continued). "In conclusion, we have found a novel surface marker in human osteosarcoma, ALCAM, which we have used to specifically target osteosarcoma cells with a novel engineered drug-loaded hybrid PLN formulation anti-ALCAM immunoconjugate." (PMID 23024593, 2012). "The proportion of maleimide DSPE was empirically determined as the lowest amount that when coupled to anti-ALCAM diabody would result in enhanced binding to osteosarcoma cells (data not shown)." (PMID 23024593, 2012). "CD166.BBζ-CAR T cells showed increased cytotoxicity to CD166/ALCAM-positive human osteosarcoma cells, but not to CD166/ALCAM-negative cells compared to non-transduced T cells, showing a correlation between CD166/ALCAM expression and cytotoxicity, and thus, specificity." (PMID 38139340, 2023). "Considering the high frequency of elevated ALCAM expression in even our small cohort of osteosarcomas, it may not be able to discriminate between high- and low-risk patients with this disease." (PMID 23024593, 2012). "In osteosarcoma cells, modified ALCAM CAR-T cells exhibit specific and potent cytotoxicity, induce regression of orthotopic osteosarcoma in vivo, and have no cytotoxic activity against healthy tissues." (PMID 37701037, 2023).
lupus nephritis (16 papers, 2020 to 2025). Glomerulonephritis in the context of systemic lupus erythematosus. "Normalizing a lupus nephritis biomarker candidate ALCAM using urinary HVEM demonstrated comparable diagnostic ability to creatinine normalization when distinguishing active lupus nephritis from inactive SLE patients." (PMID 35774777, 2022). "CD6 and ALCAM positive cells were reportedly increased in patients with lupus nephritis and were associated with SLE activity." (PMID 33748165, 2021). "For example, urinary ALCAM is a non-invasive biomarker of lupus nephritis; increased epithelial ALCAM expression supports T cell transmigration, and ALCAM expressed on B cell can navigate pathogenic B cells into the brain lesion of patients with multiple sclerosis (MS)." (PMID 36159854, 2022). "It is a ligand of CD6, and the CD6/ALCAM pathway promotes lupus nephritis via T-cell-mediated responses." (PMID 40375995, 2025). "Patients with SLE and patients with lupus nephritis (LN) showed significantly elevated ALCAM, HPX, and PRDX6 levels compared with HCs." (PMID 38915417, 2024). "Second, several CD5, CD6, and/or CD166/ALCAM gene variants have been associated with different IMIDs, such as RA, lupus nephritis, MS, psoriasis, Behçet's disease, and IBD." (PMID 35372412, 2022). "The CD166 antigen (ALCAM) exhibits one of the highest discriminatory powers for active lupus nephritis in the African-American, Caucasian, and Asian populations." (PMID 36569940, 2022). "In this paper, we focus on urine ALCAM detection as this biomarker has been extensively validated as a biomarker for lupus nephritis." (PMID 36569940, 2022). "CD6 expression was established in renal-infiltrating T cells that contribute to the pathology of lupus nephritis, while high ALCAM expression was established in structural renal cells that are subject to damage during LN disease." (PMID 34981775, 2022). "Increased excreted ALCAM levels were also measured in the urine of patients with active lupus nephritis." (PMID 33748165, 2021). "In this cross-sectional study, we performed a validation of urinary ALCAM as a potential biomarker for lupus nephritis in a Chinese lupus cohort." (PMID 32460901, 2020). "ALCAM, HPX, and PRDX6 showed significant diagnostic values, especially for lupus nephritis (LN), with areas under the receiver operating characteristic curve for LN was 0.850 for ALCAM (95% CI, 0.778–0.921), 0.781 for HPX (95% CI, 0.695–0.867), and 0.714 for PRDX6 (95% CI, 0.617–0.812)." (PMID 38915417, 2024). "In Lupus Nephritis, the ALCAM, also known as CD166, plays a pathogenic role." (PMID 38294724, 2024). "In this study, we have set the foundation for building a portable at-home detection device to noninvasively assess lupus nephritis activity: a highly sensitive LFA coupled with smartphone-based time-gated imaging to detect urine CD166/ALCAM, a leading biomarker for LN." (PMID 36569940, 2022). "Urinary ALCAM showed ability to discriminate class III/IV from V lupus nephritis." (PMID 32460901, 2020). "Urinary ALCAM is reflective of renal pathology activity index in lupus nephritis." (PMID 32460901, 2020). "The ALCAM LFA test could also be very useful in patients already diagnosed with lupus nephritis." (PMID 36569940, 2022). "Normalized fluorescence intensity values for the five biomarkers (ALCAM, OPN, TNFRSF1B, VCAM1, and VSIG4) were compared between healthy controls (HCs) and lupus nephritis (LN) patient groups." (PMID 40047601, 2025). "Among active lupus nephritis patients, urine VCAM-1 (r 0.57, P<0.0001), ALCAM (r 0.53, P<0.0001) and PF4 (r 0.50, P<0.0001) exhibited the best correlations with renal SLEDAI." (PMID 35720325, 2022). "Urine ALCAM and PF4 appear to have the greatest promise as SLE and lupus nephritis activity indicators, outperforming conventional markers in distinguishing active SLE and LN patients." (PMID 35720325, 2022).
lupus nephritis (continued). "Comprehensive aptamer screening to identify lupus nephritis urinary biomarkers across ethnicities were carried out, where CD166 antigen (ALCAM) exhibited one of the highest discriminatory powers for active nephritis in African-Americans, Caucasians and Asians." (PMID 36569940, 2022). "The role of ALCAM in lupus nephritis has been only reported in a microarray study of MRL/lpr LN mice, which revealed increased ALCAM expression in the glomeruli." (PMID 32460901, 2020).
gastric cancer (14 papers, 2011 to 2024). A primary or metastatic malignant neoplasm involving the stomach. "The membranous ALCAM expression in gastric cancer tissue and serum was associated with shorter overall survival." (PMID 29375378, 2017). "In a cohort of 142 patients with gastric cancer, the positive membrane pattern of ALCAM was found to be linked to a significantly shorter survival of the patients, and both membrane and cytoplasmic staining of ALCAM was linked to vascular invasion and nodal metastasis." (PMID 34680335, 2021). "Contrary to our results high ALCAM expression in the primary tumor was found to be associated with reduced survival or unfavourable prognostic markers in some tumor types, i.e. colorectal, oral, esophageal, pancreatic and gastric carcinomas as well as neuroblastoma." (PMID 22475274, 2012). "Significantly shorter peritoneal metastasis-free survival was seen in gastric cancer patients with high levels of ALCAM (p = 0.006)." (PMID 36614319, 2023). "More importantly, when ALCAM was knocked down from both mesothelial cells and gastric cancer cells, the interaction between the two cell types were greatly reduced compared to individual knockdown cells." (PMID 36614319, 2023). "In a comprehensive study with gastric cancer patient cohorts, ALCAM protein staining and transcript expression in tumour tissues were found to be highly raised." (PMID 34680335, 2021). "In patients with gastric cancer, serum levels of ALCAM were significantly raised compared with the control group." (PMID 34680335, 2021). "Numerous studies have explored serum ALCAM in other cancers types where elevated levels are indicative of cancer or of poorer prognosis in gastric cancer, hepatocellular carcinoma and esophageal cancer." (PMID 31695844, 2019). "Activated leukocyte cell adhesion molecule (ALCAM) has been identified as a novel potential molecular marker of gastric cancer." (PMID 27564264, 2017). "Ye M analyzed the serum soluble ALCAM (sALCAM) in large numbers of patients with gastric cancer, patients with precancerous lesions, and controls." (PMID 27564264, 2017). "Very recent data indicate that both transfection of mimics of microRNA-192 or -215 or ALCAM-specific siRNA significantly inhibit ALCAM expression and increase migration in a cell line model of gastric cancer." (PMID 21364949, 2011). "However, following knocking down ALCAM in both gastric cancer cell lines, the pace of adhesiveness to control MET5A were substantially reduced." (PMID 36614319, 2023). "MicroRNA-192 and microRNA-215 are suppressors of ALCAM expression in gastric cancer cells." (PMID 34680335, 2021). "The expression and function of ALCAM vary in different tumors; in some tumors, it plays a role in promoting cancer, and in other tumors it plays a role in suppression; some research indicated it was highly expressed in gastric cancer and promoted the migration of tumor cells." (PMID 29375378, 2017). "Similar to the pancreatic cell models, gastric cancer cell lines HGC-27 and AGS were also used to generate ALCAM knockdown cell models to examine tumour-mesothelial interaction together with ALCAM knockdown mesothelial cell line MET5A." (PMID 36614319, 2023). "Similar to gastric cancer cells, we generated an ALCAM knockdown model from PANC-1 cell line which expressed high levels of ALCAM." (PMID 36614319, 2023).
glioma (12 papers, 2012 to 2025). A benign or malignant brain and spinal cord tumor that arises from glial cells (astrocytes, oligodendrocytes, ependymal cells). "Expression of ALCAM on glioma stem cells has been previously linked to the regulation of glioblastoma invasion." (PMID 26887050, 2016). "The study identified eight co-downregulated miRNAs, three co-upregulated miRNAs, and seven genes associated with overall glioma survival, namely, KRAS, IFNB1, ALCAM, ERBB2, STAT3, FOSL1, and EN2." (PMID 36061185, 2022). "Overexpression of glioma stem cell marker ALCAM/CD166 has been shown to promote glioma progression in vivo, suggesting clinical value of its targeting for glioma management." (PMID 30701019, 2018). "For this purpose, we studied two predicted miR-138 targets for their involvement in TMZ resistance of glioma cells, namely CD166/ALCAM and BCL2L11/BIM." (PMID 26887050, 2016). "Additionally, transcripts encoding two genes thought to be potential targets for glioma treatment, ALCAM/CD166 and SHP-2, were downregulated upon piR-8041 transfection." (PMID 30701019, 2018). "As for EZR, ALCAM expression was reported correlated with the histological grade of gliomas." (PMID 29872504, 2018). "However, while we found decreased ALCAM expression levels in TMZ-resistant cells, our functional analyses did not confirm an effect of ALCAM downregulation on glioma cell sensitivity to TMZ." (PMID 26887050, 2016). "In contrast to glioma stem cells, U87 cells showed no overexpression of stem cell markers, such as SOX2, ZEB1, ATXN1, ALCAM, CD9, ITGA7, CD44 and CHI3L1." (PMID 34680293, 2021). "piR-8041 treatment decreases glioma stem cell marker ALCAM/CD166 expression, and inhibits A172 glioma cell line but not normal human astrocyte (NHA) proliferation, suggesting the clinical value of its targeting for glioma management." (PMID 31399034, 2019). "However, siRNA-mediated gene silencing of ALCAM did not confer TMZ resistance, which indicates that ALCAM downregulation alone is not sufficient to mediate TMZ resistance in glioma cells." (PMID 26887050, 2016).
glioblastoma (11 papers, 2014 to 2025). The most malignant astrocytic tumor (WHO grade IV). "According to The Cancer Genome Atlas (TCGA) online dataset, low expression levels of ALCAM correlate with shorter overall survival of glioblastoma patients (n = 504; average cut-off = 590.3; p = 5.2e−03)." (PMID 26887050, 2016). "In MG3, genes involved in endothelial regulation (ESM1, APLN, ALCAM) and ligands for αVβ3 integrin (EDIL3 and POSTN) were expressed at higher levels compared to MG1 and MG5, the latter of which recruit tumour-associated macrophages (TAM) in adult glioblastoma." (PMID 37679810, 2023). "In addition, patients with glioblastoma with high levels of ALCAM protein staining have shorter overall and disease-free survival." (PMID 34680335, 2021). "Finally, the present study allowed us to identify prognostic proteins for glioblastoma: PPP1R12A and RPS14 are favorable prognostic markers while ALCAM, ANXA11, and AltProt IP_652563 are unfavorable prognostic markers." (PMID 36333286, 2022).
metastatic disease (11 papers, 2010 to 2024). "ALCAM seems to characterize cancer stem cells (CSC) in some tumors and ALCAM was highly expressed in intestinal stem cell niche, with an association to intestinal carcinoma progression, including benign and metastatic tumors." (PMID 32085563, 2020). "ALCAM staining was detected in the majority of primary oesophageal adenocarcinoma and squamous cell carcinomas (71% of 299), metastatic lymph nodes (76% of 147), and metastatic tumours (80% of 46), and raised ALCAM levels were associated with recurrence-free and overall survival." (PMID 34680335, 2021). "Patients with multiple metastatic diseases have been shown to have a markedly elevated serum ALCAM compared with those patients who had single brain metastasis and compared with patients with non-metastatic NSCLC." (PMID 34680335, 2021). "Rather, the shed extracellular domain of ALCAM is a marker of invasive and metastatic disease and, thus, has the potential to be a clinically relevant prognostic biomarker in many epithelial cancers." (PMID 27894096, 2017). "This study has shown that the levels of ALCAM in primary tumours and metastatic tumours correlated exceptionally well (r2 = 0.504, p < 0.001) and that metastatic tumours in different sites (liver, lung, bone, brain, and lymph nodes) stained reasonably similar to primary tumours." (PMID 34680335, 2021). "Notably, we found that proteins involved in triple‐negative breast cancer (TNBC), such as GSTP1 and EPCAM, were enriched in ERα‐N metastatic tumours, while proteins typically upregulated in ERα‐P disease, such as ALCAM and KRT18, were enriched in ERα‐P as well as the ERα‐C metastatic tumours." (PMID 37854018, 2024). "ALCAM expression was examined in a tissue microarray (TMA) containing core biopsies of localized, metastatic disease and paired normal tissues." (PMID 31695844, 2019). "We further speculate that, although urine ALCAM is the predictor in non-metastatic BCa, ALCAM shed into the blood will have prognostic relevance in patients with metastatic disease." (PMID 27894096, 2017). "CD44 and ALCAM expression was detected in both mice that developed (WHIM17 and WHIM12) and mice that did not develop (WHIM23) metastatic disease." (PMID 29291741, 2018).
multiple sclerosis (10 papers, 2017 to 2024). A progressive autoimmune disorder affecting the central nervous system resulting in demyelination. "For example, CD6 and its ligand ALCAM (CD166) are considered to be risk factors for the neuro-autoimmune disease multiple sclerosis (MS)." (PMID 39026665, 2024). "CD6 and CD166/ALCAM SNPs have been identified and validated as risk factors for the development and progression of multiple sclerosis (MS), psoriasis severity, Behçet's disease risk, and inflammatory bowel disease (IBD) risk." (PMID 35372412, 2022). "ALCAM has also been indicated in mediating the blood–brain-barrier's permeability in a multiple sclerosis mouse model." (PMID 33208194, 2020). "ALCAM has been identified as a potential therapeutic target for several immune-mediated diseases, including corneal graft rejection, asthma, atopic dermatitis, food allergy, and multiple sclerosis." (PMID 37514028, 2023). "In multiple sclerosis (MS), CD38+ memory B-cell in the blood migrate toward the central nervous system by expressing the adhesion molecule ALCAM." (PMID 37144136, 2023). "In EAE, as well as in multiple sclerosis (MS), ICAM-1, VCAM-1, and ALCAM are upregulated." (PMID 32753493, 2020).